GLIS2 (GLIS family zinc finger 2)
Description:
Can act either as a transcriptional repressor or as a transcriptional activator, depending on the cell context. Acts as a repressor of the Hedgehog signaling pathway (By similarity). Represses the Hedgehog-dependent expression of Wnt4 (By similarity). Necessary to maintain the differentiated epithelial phenotype in renal cells through the inhibition of SNAI1, which itself induces the epithelial-to-mesenchymal transition (By similarity). Represses transcriptional activation mediated by CTNNB1 in the Wnt signaling pathway. May act by recruiting the corepressors CTBP1 and HDAC3. May be involved in neuron differentiation (By similarity).
Synonyms: NKL; NPHP7
Tractability: PROTAC: ubiquitination databases record sites on it.
Gene: Protein-coding gene on chromosome 16 (4,314,761 to 4,339,597, forward strand). Ensembl gene ENSG00000126603.
Subcellular location: Nucleus speckle; Cytoplasm
Subcellular location (Human Protein Atlas): Nucleoplasm; Basal body
Gene Ontology:
Molecular function: protein binding; sequence-specific double-stranded DNA binding; DNA-binding transcription activator activity, RNA polymerase II-specific; DNA-binding transcription factor activity, RNA polymerase II-specific; DNA-binding transcription repressor activity, RNA polymerase II-specific; RNA polymerase II cis-regulatory region sequence-specific DNA binding; transcription cis-regulatory region binding; DNA binding; RNA polymerase II transcription regulatory region sequence-specific DNA binding
Biological process: central nervous system development; negative regulation of DNA-templated transcription; negative regulation of smoothened signaling pathway; negative regulation of transcription by RNA polymerase II; positive regulation of DNA-templated transcription; positive regulation of transcription by RNA polymerase II; regulation of transcription by RNA polymerase II
Cellular component: nuclear speck; nucleus; cytoplasm; non-motile cilium
Genetic constraint (gnomAD): Loss-of-function variants: 14 observed, 34.36 expected, observed/expected ratio (o/e) 0.41, 90% interval 0.27 to 0.64. The synonymous counts are far from expectation, so gnomAD's model fits this gene poorly and the ratio says little. Missense variants: 675 observed, 682.85 expected, observed/expected ratio (o/e) 0.99, 90% interval 0.93 to 1.05. Synonymous variants: 368 observed, 306.75 expected, observed/expected ratio (o/e) 1.2, 90% interval 1.1 to 1.31.
Gene-disease validity (ClinGen):
ClinGen rates the evidence that GLIS2 causes each of these diseases.
nephronophthisis 7 (autosomal recessive): Moderate.
Homologues: Orthologues: chimpanzee GLIS2 (100% identical), macaque GLIS2 (99% identical), dog GLIS2 (96% identical), pig GLIS2 (95% identical), guinea pig GLIS2 (95% identical), rat Glis2 (93% identical), mouse Glis2 (93% identical), rabbit GLIS2 (77% identical), tropical clawed frog glis2 (65% identical), zebrafish glis2b (54% identical), zebrafish glis2a (44% identical), Drosophila melanogaster sug (26% identical). Paralogues in human: GLI3 (36% identical), GLI2 (35% identical), GLI1 (28% identical), GLIS3 (26% identical), GLIS1 (25% identical), ZIC3 (22% identical), ZIC5 (22% identical), ZIC2 (22% identical), ZIC1 (21% identical), ZIC4 (21% identical), ZXDC (19% identical), ZXDB (19% identical), and 2 more.
Diseases named in the same sentence as GLIS2 in open-access papers:
GLIS2 is named in the same sentence as 57 diseases in open-access papers, as found by Europe PMC text mining. Sharing a sentence is not in itself a finding about the gene and the disease. The quoted sentences say what the papers report.
acute megakaryoblastic leukemia (17 papers, 2016 to 2026). Acute megakaryoblastic leukemia (AMKL) is a form of acute myeloid leukemia (AML) that occurs predominantly in childhood and particularly in children with Down syndrome (DS-AMKL). "This study retrospectively analyzed the clinical manifestations, genetic characteristics, treatment courses, and prognoses of patients with pediatric acute megakaryoblastic leukemia (AMKL) with CBFA2T3::GLIS2 fusion treated at the Institute of Hematology, Chinese Academy of Medical Sciences." (PMID 41991315, 2026). "Several studies demonstrated that a cryptic inversion of chromosome 16 that fuses CBFA2T3 to GLIS2, is frequently (25–30%) associated with a pediatric non-Down’s syndrome (non-DS) acute megakaryoblastic leukemia (AMKL) with poor prognosis." (PMID 35681527, 2022).
leukemia (16 papers, 2013 to 2025). A malignant (clonal) hematologic disorder, involving hematopoietic stem cells and characterized by the presence of primitive or atypical myeloid or lymphoid cells in the bone marrow and the blood. "GLIS2 has been proposed as an oncogenic gene in leukemia, in which chromatin translocation causes the fusion of GLIS2 with CBFA2T3 and led to GLIS2 overexpression, and its mutation is linked with nephronophthisis in human and mice." (PMID 32483180, 2020). "In summary, while CBFA2T3::GLIS2 leukemia remains a difficult-to-treat disease, we have validated JAK2 as a selective dependency offering a new possibility for precision medicine in this very high-risk AML subset." (PMID 40470252, 2025). "Combined targeting of BCL2 (using ABT199) and the myeloid cell lymphoma-1 (MCL1) protein (using S63845) inhibits the proliferation of CBFA2T3::GLIS2 cells in vitro and abrogates leukemia progression in mouse xenografts." (PMID 37325571, 2023). "On the one hand, the introduction of CBFA2T3::GLIS2 into murine bone marrow is insufficient to induce overt leukemia in mice." (PMID 37325571, 2023). "In an endothelial cell coculture system, the expression of CBFA2T3::GLIS2 transforms human cord blood hematopoietic stem and progenitor cells (HSPCs) and leads to highly aggressive leukemia in mice." (PMID 37325571, 2023). "The frequent occurrence of the CBFA2T3::GLIS2 fusion in M7-type leukemia may be attributed to the enhanced BMP (bone morphogenetic protein) signaling which may directly contribute to megakaryocytic differentiation in leukemia cells." (PMID 41294667, 2025). "Overall, multiple molecular alterations may contribute to the phenotype of CBFA2T3::GLIS2 leukemia." (PMID 37325571, 2023). "Another pro-survival protein BCL-xL was also identified as a potential therapeutic vulnerability in erythroid and megakaryocytic lineage leukemias, including in the M07e AMKL cell line harboring CBFA2T3::GLIS2." (PMID 37325571, 2023). "To date, the exact mechanisms by which the CBFA2T3::GLIS2 fusion confers leukemia aggressiveness and chemoresistance are not completely understood." (PMID 40470252, 2025). "Moreover, extramedullary involvement both at diagnosis and in relapse is relatively frequent in CBFA2T3::GLIS2-positive leukemia patients compared with AML patients without this genetic aberration." (PMID 40565358, 2025). "The role of miRNA changes in leukemia initiation by CBFA2T3::GLIS2 is not well defined." (PMID 37325571, 2023). "Studies have indicated that CBFA2T3::GLIS2 is the most common chimeric oncogene in non-DS-AMKL, representing the highly aggressive nature of leukemia." (PMID 40547921, 2025). "Similar results were obtained on primary leukemia cells isolated from AML patients, being the IC50 of the GLIS2-positive leukemia and negative primary cells 13.6 and 41.6 μM, respectively." (PMID 28109323, 2017). "Furthermore, CD56+CD45−-cells are always suggestive of BM metastases of various solid tumors, and even BM differentiation between leukemia and nonhematopoietic tumors is one of the main challenges in CBFA2T3::GLIS2-positive AMKL diagnosis." (PMID 40565358, 2025). "CBFA2T3::GLIS2 is not specific to AMKL and occurs in diverse morphologic subtypes of de novo AML (except for acute promyelocytic leukemia (APL) and leukemia with erythroid differentiation), overall found in approximately 8.4% of cytogenetically normal AML cases." (PMID 37325571, 2023).
nephronophthisis (13 papers, 2015 to 2025). Progressive tubulointerstitial injury, inherited in an autosomal recessive pattern, caused by mutations in genes involved in ciliary function, which may result in an end stage renal failure. "Glis2 was selected for biological validation based on its robust expression along the entire nephron, its association with a ciliopathic nephronophthisis phenotype and its strong statistical association with the “CDCA pattern” TRAP gene set." (PMID 38693102, 2024). "Replicative senescence in tubular cells, which leads to secretion of pro-inflammatory molecules, has been shown to cause extensive kidney damage in Glis2/Nphp7 knockout mice (see section “Pathophysiology of Nephronophthisis”)." (PMID 34055783, 2021). "Glis2/NPHP7 is mutated in nephronophthisis, a hereditary condition associated with cystic kidney disease, renal fibrosis, and various extrarenal manifestations." (PMID 26083374, 2015). "First, GLIS2 loss causes nephronophthisis, a renal ciliopathy." (PMID 34705506, 2021). "GLIS2 mutation has been shown to be related with nephronophthisis in human and mice." (PMID 32483180, 2020). "A nephronophthisis-like phenotype in human and mice was found associated with a mutation in the GLIS2 gene, with severe renal fibrosis and atrophy resulting from upregulation of fibrosis related genes and increased apoptosis in the GLIS2 mutant kidneys." (PMID 30791866, 2019). "Loss of Glis2 induces the growth of cysts caused by nephronophthisis." (PMID 28859164, 2017). "Finally, Glis2 is a causative gene for nephronophthisis, a ciliopathy related kidney disease." (PMID 38693102, 2024). "There is also evidence that the transcription factor GLIS2 regulates Wnt4 expression, with homozygous mutant GLIS2-/- mice and GLIS2-knockdown IMDC3 cells showing upregulated Wnt4 expression and GLIS2 mutations linked to Nephronophthisis 7 in humans and mice." (PMID 32365994, 2020). "Mutations of Glis2/NPHP7 are a rare cause for nephronophthisis (NPH), an autosomal recessive disease associated with end-stage renal disease and variable extrarenal manifestations; so far, only two families with Glis2/NPHP7 mutations and typical NPH manifestations have been identified." (PMID 26083374, 2015). "GLIS2 and ZBTB5, poorly characterized TFs, are implicated in processes like epithelial–mesenchymal transition and nephronophthisis but not in the NF-κB system." (PMID 39753783, 2025).
acute myeloid leukemia (10 papers, 2013 to 2025). Acute myeloid leukemia (AML) is a group of neoplasms arising from precursor cells committed to the myeloid cell-line differentiation. "We recently discovered FOLR1 to be expressed in a highly refractory infant acute myeloid leukemia (AML) driven by the CBFA2T3::GLIS2 fusion." (PMID 40919994, 2025). "CBFA2T3::GLIS2 fusion positive pediatric acute myeloid leukemia (AML) remains one of the worst prognostic AML subgroups." (PMID 40470252, 2025). "CBFA2T3 expression levels are elevated in lymphoid and myeloid based cell lines, and genetic CBFA2T3 fusion with RUNX1 or GLIS2 accelerates acute myeloid leukemia and megakaryoblastic leukemia." (PMID 38786053, 2024). "By the way, GLIS2, the other intersected target gene of miR-138-2-3p, is a member of GLI-similar zinc finger protein family and is closely linked with acute myeloid leukaemia, has been also noted to correlated with tumor progression." (PMID 32293515, 2020).
Down syndrome (8 papers, 2017 to 2025). "CBFA2T3::GLIS2, resulting from cryptic inversion of chromosome 16, is the most frequent chimeric oncogene in non-Down syndrome AMKL." (PMID 40565358, 2025). "In non-Down syndrome children with AMKL, CBFA2T3::GLIS2 is the most frequent chimeric oncogene identified to date." (PMID 40565358, 2025).
breast cancer (6 papers, 2013 to 2024). A primary or metastatic malignant neoplasm involving the breast. "Furthermore, high expression of GLIS2 target genes serves as a hallmark of claudin-low breast cancers." (PMID 34705506, 2021). "To determine whether high expression of the GLIS2 signature is a hallmark of claudin-low tumors across breast cancers in general, we compared the expression of GLIS2 target genes in 1082 breast cancers, using a public dataset from The Cancer Genome Atlas (TCGA)." (PMID 34705506, 2021). "CircRNA circIKBKB promotes breast cancer bone metastasis through sustaining NF-κB/bone remodeling factor signaling CircRNA GLIS2 promotes colorectal cancer cell motility via activation of the NF-κB pathway." (PMID 36609391, 2023). "To further analyze primary ciliogenesis and GLIS2 in claudin-low human breast cancers, we established a tumor biobank by characterizing tumor samples in a previously assembled TNBC biobank." (PMID 34705506, 2021). "A pan cancer analysis showed that GLIS2 exhibited higher expression in pancreas cancer, colon cancer, breast cancer, and brain cancer, in comparison with their corresponding normal tissues, suggesting a wide oncogenic role in multiple cancers for GLIS2." (PMID 32483180, 2020). "Additional studies are needed to determine the molecular basis of the interaction between GLIS2 and CDC7 as well as the role of rs13447455 in breast cancer susceptibility." (PMID 30823486, 2019). "The resulting primary cilium promote ubiquitination and inactivation of a transcriptional repressor(GLIS2) to promote MaSC stemness and induce the proliferative and tumorigenic capacities of the mammary tumor initiating cells (MaTICs) of claudin-low breast cancers." (PMID 37490178, 2024). "Moreover, GLIS2 inactivation is required to induce the proliferative and tumorigenic capacities of the mammary tumor–initiating cells (MaTICs) of claudin-low breast cancers." (PMID 34705506, 2021). "Notably, we found that a GLIS2 signature identifies claudin-low tumors from other breast cancer subtypes as effectively as the previously identified claudin-low signature." (PMID 34705506, 2021).
ciliopathies (6 papers, 2013 to 2024). "While most ciliopathy-associated molecules are found in the cilium, Glis2/NPHP7 presumably localizes to the nucleus." (PMID 26083374, 2015). "Glis3 deficiency in humans and mice is also associated with typical ciliopathy phenotypes, including cystic kidney disease, suggesting that both Glis2/NPHP7 and Glis3 are required for normal ciliary function and/or ciliary signaling." (PMID 26083374, 2015). "Mutant mice of Nphp7/Glis2, which encodes the transcription factor Gli-similar protein 2 (GLIS2), also show severe renal atrophy and fibrosis similar to human renal atrophy 73, highlighting the link between ciliopathy and Hh." (PMID 37629084, 2023). "In addition, depletion of Glis2/NPHP7 causes renal cysts and fibrosis in mice and typical ciliopathy phenotypes in zebrafish, supporting the involvement of Glis2/NPHP7 in NPH." (PMID 26083374, 2015). "Hence, NPH together with related syndromes have been collectively termed ciliopathies, and Glis2/NPHP7, although predominantly present in the nucleus, has also been identified in the cilium." (PMID 26083374, 2015).
colorectal cancer (6 papers, 2020 to 2023). A primary or metastatic malignant neoplasm that affects the colon or rectum. "A recent study showed that the expression circular GLIS2 (circGLIS2) was significantly higher in colorectal cancer, the third most common cancer globally." (PMID 35681527, 2022). "A recent study reported that, in addition to circGLIS2, linear GLIS2 RNA also plays a role in colorectal cancer." (PMID 35681527, 2022). "For example, circRNA GLIS2 promotes colorectal cancer cell motility via activation of the NF-κB pathway." (PMID 33195693, 2020). "So far, the involvement of a number of circular RNAs including ciRS-7-A, circITGA7, PIP5K1A, GLIS2, and HIPK3 in the development of colorectal cancer has been identified." (PMID 34479583, 2021).
lung carcinoma (5 papers, 2014 to 2024). "This overexpression aims to reduce the inhibitory impact of miR-3142 on GLIS family zinc finger 2 (GLIS2), which in turn prevents the activation of the AKT pathway and thus hinders the progression of lung cancer." (PMID 38338859, 2024). "To further check GLIS2’s function on PUMA expression, we investigated four other cell lines, including one lung cancer cell line, A549, one cervix cancer cell line, HeLa, and two liver cell lines, HL7702 and HepG2." (PMID 32483180, 2020). "Interestingly, GLIS2, another regulatory target of NME2, has been demonstrated to function as a negative regulator of Wnt/beta-catenin signaling pathway and was crucial for lung cancer metastasis to brain." (PMID 25249619, 2014).
liver fibrosis (4 papers, 2016 to 2024). "Our top ranking feature, GLIS3, belongs to the same family with another candidate regulator, GLIS2, and, together, they have been found to be associated with liver fibrosis." (PMID 27818995, 2016). "The role of Gli-similar 2 (Glis2) in hepatic fibrosis (HF) is controversial." (PMID 37394585, 2023).